AIM2 (absent in melanoma 2)
Diseases named in the same sentence as AIM2 in open-access papers (continued):
Sharing a sentence is not in itself a finding about the gene and the disease.
cancer (continued). "Although there is little literature on the estrogen receptors (ERalpha, ERbeta, and GPR30) for cancer and in connection with NLRP3, their impact on NLRC4 and AIM2 is not described yet." (PMID 32645874, 2020). "To further explore the anti-carcinogenic roles of AIM2 in colorectal tumorigenesis, we firstly analyzed AIM2 protein expression in human CRC tissues and para-cancer normal tissues using Immunohistochemistry (IHC) analysis." (PMID 33291082, 2020). "Additionally, AIM2 can engage alternative signaling pathways, such as AKT and NF-κB, independent of inflammasome activation, to modulate cancer progression." (PMID 39744568, 2025).
bacterial infection (24 papers, 2012 to 2025). "However, to date, the activation of AIM2 caused by bacterial infection still needs further study and exploration because the previous findings illustrate only the biological relevance of AIM2 in host defense." (PMID 35132346, 2022). "Accordingly, the inhibition of the NLRP3 and AIM2 inflammasomes by ethanol may contribute to the increased incidence of bacterial infections associated with excessive use of alcohol." (PMID 24244322, 2013). "While during bacterial infection, DNA is delivered to AIM2 with the assistance of interferon-inducible GTPases, the role of AIM2 inflammasome in response to fungi is less clear." (PMID 41249509, 2025). "Based on existing studies, the overexpression of GBP2 can promote the activation of AIM2 during bacterial infection." (PMID 41199598, 2025). "Two essential prerequisites for AIM2 inflammasome activation in the context of bacterial infection are the access of bacteria to the cytoplasm and the subsequent release of bacterial DNA through bacteriolysis." (PMID 39076969, 2024). "The activation of the AIM2 inflammasome during bacterial infections is primarily attributed to its ability to detect microbial dsDNA." (PMID 39076969, 2024). "AIM2 was identified as the receptor involved in inflammasome activation in response to the recognition of cytosolic DNA during bacterial infections leading to the production of IL-1β and IL-18, and pyroptosis." (PMID 36033879, 2022). "GBP2 has been reported to induce cytoplasmic lysis and DNA release during bacterial infection and to promote the activation of melanoma infection factor 2 (AIM2) by the inflammasome." (PMID 36115937, 2022). "In the context of bacterial infection, GSDMD is essential for the F. novicida-triggered AIM2 inflammasome activation, the deficiency of GSDMD increases the mouse susceptibility to the F. novicida infection." (PMID 31035661, 2019). "In the context of bacterial infection, AIM2 is recognized as mainly responsive to the Francisella infection and partially involved in the infection with Mycobacteria and Listeria." (PMID 31035661, 2019). "For example, activation of AIM2 inflammasome was shown to be mediated by guanylate-binding proteins after bacterial infection." (PMID 29615985, 2018). "Despite the reported roles of AIM2-mediated immunity in both viral and bacterial infections, the factors regulating AIM2-mediated cell death remain poorly understood." (PMID 25665578, 2015). "C. trachomatis infection at high MOIs can be detected by AIM2 in macrophages, which activates caspase-1 in cells upon bacterial infection but is also known to drive caspase-3-dependent apoptosis—a less inflammatory mode of cell death—in caspase-1-deficient cells." (PMID 39772728, 2025). "Since AIM2 activation can trigger PANoptosis during dsDNA viral and bacterial infection, we further determined whether BHRF1-mediated AIM2 inflammasome activation affects cell death during EBV lytic replication." (PMID 40982560, 2025). "AIM2 forms inflammasome complex by viral or bacterial infections." (PMID 35887028, 2022). "The AIM2 inflammasome is a detector of cytosolic double-stranded DNA (dsDNA) and plays an important role in the coordination of the immune defense against intracellular bacterial infections." (PMID 34072918, 2021). "Whether the host DNA also contributes to the activation of the AIM2 inflammasome during bacterial infection remains unclear." (PMID 31035661, 2019). "The activation of AIM2 and NLRP3 inflammasomes typically plays positive roles in host defense against bacterial infection." (PMID 34869331, 2021). "In response to DNA in the cytoplasm in viral and bacterial infection, the sensor AIM2 recruits ASC and Casp1 to form the AIM2 inflammasome complex, which also leads to the autocleavage of Casp1 to generate Casp1 p10 and p20." (PMID 33613874, 2021).
bacterial infection (continued). "For instance, bacterial infection is recognized by nucleotide-binding domain, leucine-rich-containing family, pyrin domain-containing-1 (NLRP1), NLRP3, NLRP4, and absent in melanoma 2 (AIM2)." (PMID 23964268, 2013). "However, inflammasomes including AIM2, NLRP3 and NLRC4 are also expressed in neutrophils and involved in IL-1β secretion during bacterial infection." (PMID 34017331, 2021). "Even though the role of AIM2 in HPV infection has been only marginally addressed, it is well established that the AIM2 inflammasome is crucial for the immune response to viral and bacterial infections." (PMID 31861809, 2019). "Recently, the absent in melanoma 2 (AIM2) has been identified as a novel inflammasome component involved in the recognition of cytosolic DNA during viral and bacterial infection such as Listeria monocytogenes and Francisella tularensis." (PMID 22723924, 2012).
cardiovascular diseases (10 papers, 2018 to 2025). "Therapeutic targeting of AIM2 and its downstream pathways holds significant potential for stabilizing atherosclerotic plaques, reducing inflammation, and improving cardiac function, thereby offering promising strategies for treating these cardiovascular diseases." (PMID 39158380, 2025).
neurodegenerative disease (8 papers, 2019 to 2025). A disorder of the central nervous system characterized by gradual and progressive loss of neural tissue and neurologic function. "Because development of certain neurodegenerative diseases, such as AD, is associated with aging and vascular dysfunction, it remains to be seen whether the expression of AIM2 gene and the functions of the AIM2 protein in the CNS decrease with the age." (PMID 31771614, 2019). "Promising drug candidates targeting AIM2 signaling pathways have also emerged for potential clinical applications in neurodegenerative disease treatment." (PMID 39076969, 2024). "The investigation of AIM2 signaling in neurodegenerative diseases has unveiled its multifaceted roles in various pathological conditions." (PMID 39076969, 2024). "These interactions provide insights into the multifaceted roles of AIM2 in neurodegenerative diseases." (PMID 39076969, 2024). "Despite significant advances in understanding the role of AIM2 in neuroinflammation and neurodegenerative diseases, several limitations and challenges persist in the current research landscape." (PMID 39076969, 2024). "Targeting of AIM2 signaling pathways presents a promising therapeutic avenue for neuroprotection in neurodegenerative diseases, with various strategies focusing on regulating AIM2 expression, activation, and downstream signaling pathways." (PMID 39076969, 2024). "Several drug candidates targeting AIM2 signaling pathways offer promise for clinical applications in the treatment of neurodegenerative diseases." (PMID 39076969, 2024). "AIM2 activation has been observed in various pathological conditions, such as neurodegenerative diseases, diabetes and heart failure." (PMID 39076969, 2024). "Our study uncovers an entirely new regulatory mechanism by which AIM2 modulates neuroinflammation and neurodegenerative diseases." (PMID 33710283, 2021). "An overview of studies on the AIM2 inflammasome in neurodegenerative diseases." (PMID 39076969, 2024). "In conclusion, a profound understanding of AIM2 in neurodegenerative diseases may facilitate the development of effective interventions to mitigate neuronal damage and slow disease progression." (PMID 39076969, 2024). "Similar to several other neurodegenerative diseases, evidence ofinflammasome activation through Nlpr3 expression was detected inthe Tpp1–/– mouse brain, including transcriptional upregulation of key components ofthat multimolecular signaling complex (i.e., Aim2,Pycard, Naip members, andPanx1)." (PMID 31003587, 2019). "The consequences of AIM2 activation can provide a protective effect that goes beyond canonical ASC speck formation and IL-1β secretion, highlighting diversity in inflammasome functions in neurodegenerative diseases." (PMID 41386298, 2025). "In addition to NLRP3, other inflammasomes such as AIM2, NLRC4 and NLRP1 and their downstream effector molecules have been found to play pathological roles in neurodegenerative diseases." (PMID 39710713, 2024). "Suppression of T1 IFN response by Aim2 and AIM2 proteins in the CNS may be important to keep the levels of the T1 IFN-inducible negative regulator proteins (murine p202 and human IFI16-β and POP3) below a threshold to suppress neuroinflammation-related neurodegenerative diseases." (PMID 31771614, 2019).
immune diseases (7 papers, 2018 to 2025). "Although scientists have found that AIM2 activation in keratinocytes drives the development of many immune diseases, some other skin cells have the opposite expression; for example, AIM2 is restrictedly expressed in melanocytes in normal skin." (PMID 36742336, 2023). "Accumulating data suggest that inflammasomes, mainly NLRP3, NLRP1, and AIM2, are involved in the generation of tissue damage and immune dysfunction after trauma." (PMID 30166988, 2018). "Although inflammasomes can be activated by many members of the NLR family, this review will focus mainly on the NLRP3 inflammasome and NLRP1, NLRC4 and proteins absent in melanoma 2 (AIM2), also important in many immune diseases." (PMID 35457026, 2022). "The upregulation of NEAT1 has been shown to promote the release of several inflammasomes (NLRP3, NLRC4, and AIM2) and pro-inflammatory cytokines (CXCL10, IL-6, and IL-1β), resulting in an immune response in inflammatory and immune diseases." (PMID 35127819, 2021).
renal diseases (7 papers, 2018 to 2025). "AIM2 inflammasome is linked to kidney disease and plays a key role in regulating renal injury, inflammation, and fibrosis by assembling the multiprotein platforms for caspase activation." (PMID 37200367, 2023). "There is also evidence that NLRP1, NLRC4, and AIM2 inflammasomes are associated with certain forms of kidney disease." (PMID 37500614, 2023). "AIM2 is a pivotal receptor in the mediation of pyroptosis and plays a significant role in various kidney diseases." (PMID 39659523, 2024). "Extensive literature review was performed, and flavonoids were screened by molecular docking analyses followed by molecular dynamic simulations against kidney diseases by targeting AIM2." (PMID 37200367, 2023). "In conclusion, the current work suggested that the reported compound Procyanidin (ID:107876) are effective in kidney disease by targeting AIM2." (PMID 37200367, 2023). "Though extensive in silico analyses including molecular docking analyses and molecular dynamic analyses seem to be enough to conclude that Procyanidin (ID:107876) may be the potent option for kidney disease by targeting AIM2." (PMID 37200367, 2023). "The observed novel results based on extensive computational analyses may be significant for potential drug design against renal disorders by targeting AIM2." (PMID 37200367, 2023). "AIM2, as a well-defined pyroptosis receptor, has been demonstrated to mitigate renal injury in ischaemia/reperfusion-induced AKI mice by inhibiting the AIM2 inflammasome, suggesting that AIM2 may mediate pyroptosis in renal proximal tubule during renal diseases." (PMID 39659523, 2024). "Interferon inducible protein 2 (AIM2) is a non-NLR protein expressed in the kidney and extensively characterized regarding renal diseases." (PMID 37200367, 2023).
metabolic disease (6 papers, 2019 to 2025). A congenital disorder (due to inherited enzyme abnormality) or acquired (due to failure of a metabolically important organ) disorder resulting from an abnormal metabolic process. "AIM2, as the sensor of dsDNA, is drawing more attention nowadays, as oxidative stress and DNA damage are found to play pivotal role in metabolic disorders." (PMID 40433411, 2025). "These insights highlight the complex and context‐dependent functions of AIM2, providing therapeutic insights for managing metabolic diseases." (PMID 39158380, 2025). "Other inflammasomes and molecules related to the activation cascade (e.g., CARD8, AIM2, IFI16, CASP-1, and IL-1β) have also been found to be associated with a variety of infections and metabolic diseases." (PMID 36105941, 2022). "In summary, studies should be carried out to illustrate the role and mechanism of other inflammasomes, including AIM2, NLRP1, NLRP6 and NLRC4 inflammasomes, in metabolic disorders." (PMID 40433411, 2025).
infectious disease (5 papers, 2021 to 2024). A disorder directly resulting from the presence and activity of a microbial, viral, or parasitic agent in humans. "Studies regarding human genetic variants of AIM2 are rare in infectious diseases." (PMID 33868225, 2021).
neurological disorders (4 papers, 2022 to 2025). "The ability of AIM2 to recognize dsDNA in conjunction with the cGAS-STING pathway and initiate inflammasome assembly underscores its importance in neuroinflammatory processes, highlighting its potential as a therapeutic target in various neurological disorders." (PMID 40781073, 2025).
inflammation (3 papers, 2019 to 2024). Aberrant reaction of the microcirculation characterized by movement of fluid and leukocytes from the blood into extravascular tissues. "have suggested that the expression levels of Hepatic AIM2 were positively correlated to the severity of liver inflammation, and the expression of IL-18 was increased after AIM2 sensed HBV in hepatocytes." (PMID 38817443, 2024).
adenocarcinoma (2 papers, 2021 to 2024). A common cancer characterized by the presence of malignant glandular cells. "We first analysed adenocarcinoma patients according to COPD and AIM2 score." (PMID 34084280, 2021). "We found that AIM2 inflammasome and caspase-11 underlie lung inflammation typical of smoking COPD patients who have a higher hazard ratio in terms of AIM2-related expression, implying lower survival rate than non-smoker, non-COPD adenocarcinoma patients." (PMID 34084280, 2021). "We found that AIM2 was expressed at higher levels in cancerous tissues of both non-COPD and COPD adenocarcinoma tissues compared to normal tissues." (PMID 34084280, 2021). "Taken altogether, these data, similarly to what observed in mice, imply that AIM2 in COPD adenocarcinoma patients could underlie lung inflammation typical of smoking patients who have a higher hazard ratio to survive less than non-smoker, non-COPD adenocarcinoma patients." (PMID 34084280, 2021).
gynecological diseases (1 paper, 2026). "We comprehensively summarize the molecular mechanisms of inflammasome activation-particularly NLRP3, AIM2, and IFI16-and their dual roles in inflammatory injury and immune regulation across gynecological diseases." (PMID 42079573, 2026).
head and neck tumors (1 paper, 2024). "In this study, it was found that IL-1α, IL-1β, IL1R1, IL1RL1, IL1F10, IL33, CASP1, and AIM2 were highly expressed in head and neck tumors, while IL1RN, IL1RAPL1, IL1RAPL2, IL18BP, IL18R1, and IL18RAP were low in expressed, which is consistent with previous literature." (PMID 39461030, 2024).
intestinal disease (1 paper, 2023). "The differences in AIM2 on gastric and intestinal disease further exemplify the diverse roles of AIM2 and suggest that the gastrointestinal tract may be finely tuned to a physiological threshold of AIM2 expression/activation for homeostasis whereby disrupting this balance compromises integrity." (PMID 36967659, 2023).
peripheral nerve disorders (1 paper, 2026). "Emerging evidence identifies nonredundant roles for NLRP6 and AIM2 inflammasomes in peripheral nerve disorders, activated through divergent upstream sensors yet converging on shared pyroptotic execution." (PMID 41574659, 2026). "While IFI16 shows no documented pyroptotic activity in neural tissues, AIM2 has been thoroughly investigated in peripheral neuropathies." (PMID 41574659, 2026).
respiratory diseases (1 paper, 2022). "Of the respiratory diseases discussed here, we highlight the host initiation of pyroptosis through the non-canonical inflammasome, as well as the AIM2 and NLRP3 inflammasomes." (PMID 35626718, 2022).
AIM2 also shares sentences with these, for which no sentence is quoted: idiopathic pulmonary fibrosis (5 papers); squamous cell carcinoma (5); atopic dermatitis (4); cerebral artery (4); chronic periodontitis (4); auto-inflammatory syndromes (3); discoid lupus erythematosus (3); endometrial cancer (3); sarcoma (3); breast tumor (2); dengue (2); gastric tumor (2); Hepatic steatosis (2); hyperlipidaemia (2); hypopharyngeal squamous cell carcinoma (2); ileus (2); leishmaniasis (2); lymphoma (2); mesothelioma (2); metabolic syndrome (2); Nephropathy (2); pancreatic adenocarcinoma (2); pneumonia (2); prostate adenocarcinoma (2); rectal cancer (2); Acidosis (1); acute lymphoblastic leukemia (1); Aicardi-Goutières syndrome (1); alcohol dependence (1); allergic contact dermatitis (1).
A further 69 diseases each share a sentence with AIM2 in 1 paper.